TRIM46 (tripartite motif containing 46)
Description:
Microtubule-associated protein that is involved in the formation of parallel microtubule bundles linked by cross-bridges in the proximal axon. Required for the uniform orientation and maintenance of the parallel microtubule fascicles, which are important for efficient cargo delivery and trafficking in axons. Thereby also required for proper axon specification, the establishment of neuronal polarity and proper neuronal migration.
Synonyms: GeneY; TRIFIC; FLJ23229
Tractability: PROTAC: ubiquitination databases record sites on it; its protein half-life has been measured.
Gene: Protein-coding gene on chromosome 1 (155,173,787 to 155,184,971, forward strand). Ensembl gene ENSG00000163462.
Subcellular location: Cell projection, axon; Cytoplasm, cytoskeleton
Subcellular location (Human Protein Atlas): Microtubule ends; Mitotic spindle; Primary cilium transition zone; Centrosome; Cytokinetic bridge; Cytosol
Pathways (Reactome):
Immune System: Interferon gamma signaling
Gene Ontology:
Molecular function: zinc ion binding
Biological process: anterograde synaptic vesicle transport; axonogenesis; microtubule bundle formation; negative regulation of axon extension; neuron migration; positive regulation of anterograde dense core granule transport; regulation of protein localization
Cellular component: main axon; axon; axon cytoplasm; axon initial segment; cytoskeleton; proximal neuron projection
Genetic constraint (gnomAD): Loss-of-function variants: 17 observed, 71.97 expected, observed/expected ratio (o/e) 0.24, 90% interval 0.16 to 0.35. The upper end of that interval is the gene's LOEUF score, 0.35, which puts it in group 1 of 6, group 1 being the genes least tolerant of losing a copy. Missense variants: 675 observed, 1,045.8 expected, observed/expected ratio (o/e) 0.65, 90% interval 0.61 to 0.69. Synonymous variants: 391 observed, 442.39 expected, observed/expected ratio (o/e) 0.88, 90% interval 0.81 to 0.96.
Homologues: Orthologues: chimpanzee TRIM46 (100% identical), macaque TRIM46 (99% identical), dog TRIM46 (99% identical), mouse Trim46 (98% identical), rabbit TRIM46 (96% identical), rat Trim46 (96% identical), guinea pig TRIM46 (87% identical), pig TRIM46 (76% identical), zebrafish trim46a (58% identical), zebrafish trim46b (57% identical), tropical clawed frog TRIM46 (31% identical). Paralogues in human: TRIM36 (41% identical), TRIM9 (25% identical), TRIM67 (23% identical), TRIM33 (18% identical), TRIM24 (16% identical), TRIM37 (15% identical), TRIM3 (14% identical), TRIM71 (14% identical), TRIM2 (13% identical), TRIM66 (13% identical), TRIM8 (13% identical), TRIM28 (13% identical), and 68 more.
Diseases named in the same sentence as TRIM46 in open-access papers:
TRIM46 is named in the same sentence as 27 diseases in open-access papers, as found by Europe PMC text mining. Sharing a sentence is not in itself a finding about the gene and the disease. The quoted sentences say what the papers report.
breast carcinoma (7 papers, 2016 to 2024). "One of the 65 new breast cancer risk loci identified via GWAS—rs4971059—is shown to activate the expression of ubiquitin ligase TRIM46, which targets histone deacetylase HDAC1 for ubiquitination and degradation." (PMID 37175659, 2023). "Mmu-miR-1894-3p and the shRNA knocked down the expression of Trim46 and reduced the recruitment of Trim46 to the cell membrane of both the mouse and human breast cancer cells." (PMID 27110773, 2016). "Furthermore, we found that a group of variants on chromosome 1 (rs1202980, rs60220284, and rs45574833) located in the C4BPA, LOC107985251, and TRIM46 genes are related to breast cancer." (PMID 36859360, 2023). "It has been found that TRIM46 was involved in the proliferation and migration of mouse and human breast cancer cells and TRIM46 could be inhibited by mmu-miR-1894-3p." (PMID 32117427, 2019). "The cell growth curves and metastasis assay indicated that Trim46-shRNA also inhibited cell proliferation and decreased the metastasis nodes in lung tissues (n = 8, p < 0.01), suggesting that Trim46 was the major target of mmu-miR-1894-3p for inhibition of breast cancer cell metastasis." (PMID 27110773, 2016). "TRIM46, which is affiliated in the tripartite motif (TRIM) protein family, acts as an E3 ligase that targets HDAC1 and promotes carcinogenesis and chemoresistance in breast cancer." (PMID 38095640, 2023). "Moreover, knockdown of human Trim46 also prohibited the cell proliferation, migration and wound healing of MBA-MD-231 human breast cancer cells." (PMID 27110773, 2016).
gout (5 papers, 2017 to 2024). A condition characterized by painful swelling of the joints, which is caused by deposition of urate crystals. "TRIM46 was identified as the most prevalent susceptibility gene with a promotion factor for gout among these mast cells (beta = 1.34)." (PMID 38831441, 2024). "Another Chinese study showed that rs10821905 of A1CF gene, rs2941484 of HNF4G gene, and rs4971101 and rs2070803 of TRIM46 gene were associated with susceptibility to gout." (PMID 30123371, 2018). "These factors could interact with specific variants of the TRIM46 gene to jointly regulate the risk of gout by altering the level of inflammation within the body, the metabolic pathway of uric acid, or the sensitivity of cells to oxidative stress." (PMID 38831441, 2024). "This study also identified 22 methylation sites related to gout, and genes that may increase the risk of gout, such as TRIM46, MAP3K11, KRTCAP2 and TM7SF2." (PMID 38831441, 2024). "In addition, A1CF and TRIM46 were identified as associated with gout in the Chinese population for the first time (PFDR < 0.05)." (PMID 28252667, 2017). "In addition, the variant locus on the TRIM46 gene may interact with a history of smoking, thereby increasing the risk of developing gout." (PMID 38831441, 2024). "Moreover, distinct alleles of the TRIM46 gene may modify the effects of smoking on uric acid levels or inflammatory response, thereby increasing the risk of gout." (PMID 38831441, 2024). "Simultaneously, long-term exposure to environmental factors like air pollution could increase oxidative stress and inflammation, interacting with TRIM46 variants in regulating the cellular capacity to handle urate crystals, thereby jointly increasing the risk of gout." (PMID 38831441, 2024). "We discovered that TRIM46 had a positive correlation with gout (beta = 1.34); therefore, upregulation of DNAm on the cg15699386 locus would result in an increase in TRIM46 expression (beta = 0.24), which would increase the risk of gout development (beta = 0.43)." (PMID 38831441, 2024). "We identified 17 association signals for gout at unique genetic loci, including four genes related by protein-protein interaction network (PPI) analysis: TRIM46, THBS3, MTX1, and KRTCAP2." (PMID 38831441, 2024). "This study identified 17 genetic loci associated with gout, including four genes related by protein-protein interaction network (PPI) analysis: TRIM46, THBS3, MTX1 and KRTCAP2." (PMID 38831441, 2024). "Three LD blocks existed in chromosome 1 for the variants relating to gout, which were composed of genes DNAJC16, AGMAT (first block), PDZK1, CD160, NUDT17 (second block), TRIM46, MUC1, MTX1, and ASH1L (third block)." (PMID 36221101, 2022). "Six of the genes (A1CF, GCKR, ABCG2, TRIM46, SLC17A1 and HNF4G (novel gout-associated gene)) were still significantly associated with gout in males after multiple correction (all PFDR < 0.05)." (PMID 28252667, 2017). "The study also found that genes such as TRIM46, MAP3K11, KRTCAP2, and TM7SF2 could potentially elevate the risk of gout." (PMID 38831441, 2024). "Surprisingly, variants on chromosome 1, such as rs7546668 (DNAJC16), rs10927807 (AGMAT), rs9286836 (NUDT17), rs4971100 (TRIM46), rs4072037 (MUC1), and rs2974935 (MTX1), showed significant associations with gout in both discovery and replication cohorts (all p-values < 1e−8)." (PMID 36221101, 2022). "Moreover, rs9286836 (NUDT17) and rs4971100 (TRIM46), rs4072037 (MUC1) and rs2974935 (MTX1) also revealed significant associations with gout (all p-values <1e−8)." (PMID 36221101, 2022). "In females, ABCG2 and TRIM46 contributed to the risk of gout (both P < 0.05), but neither was significant after multiple correction (both PFDR > 0.05)." (PMID 28252667, 2017). "Among the fourteen genes, six genes (ABCG2, SLC2A9, TRIM46, SLC17A1, A1CF and SLC17A4) affected both the elevation of the serum urate level and the development of gout from hyperuricemia and were identified as risk factors for gout." (PMID 28252667, 2017).
gout (continued). "By comparing the unique regulatory role of TRIM46 with existing theories on the pathogenesis of gout, we discovered that TRIM46 might provide new insights into understanding gout inflammation, particularly in analyzing the molecular mechanisms of macrophage responses induced by MSU crystals." (PMID 38831441, 2024). "Additionally, TRIM46, by regulating microtubule dynamics, could indirectly affect macrophages’ ability to phagocytose and process monosodium urate crystals (MSUc), which is crucial for modulating the inflammatory response in gout." (PMID 38831441, 2024). "TRIM46’s involvement in this pathway could have a comprehensive impact on the production of inflammatory cytokines by macrophages, microtubule dynamics regulation, and cell polarization, thereby regulating the pathological process of gout in terms of uric acid metabolism and inflammatory response." (PMID 38831441, 2024). "This study performed a GWAS in a large sample size and found genes DNAJC16, AGMAT, NUDT17, TRIM46 MUC1, and MTX1 on chromosome 1 relating to gout disease." (PMID 36221101, 2022). "Surprisingly, variants on chromosome 1 located in genes DNAJC16, AGMAT, NUDT17, TRIM46, MUC1 and MTX1 showed significant associations with gout, which finding had not been reported before." (PMID 36221101, 2022). "Six genes (A1CF, ABCG2, SLC2A9, TRIM46, SLC17A1 and SLC17A4) exhibited effects on the development of gout from hyperuricemia in males (all P < 0.05), but none of them exhibited such effects in females (all P > 0.05)." (PMID 28252667, 2017).
lung adenocarcinoma (5 papers, 2022 to 2025). A carcinoma that arises from the lung and is characterized by the presence of malignant glandular epithelial cells. "Here, TRIM46 amplification was found in lung adenocarcinoma (LUAD) tissues and TRIM46 amplification was significantly associated with a poor survival rate." (PMID 35354796, 2022). "Furthermore, TRIM46 amplification is associated with decreased PHLPP2 levels, increasing p‐AKT levels and promoting glycolysis in lung adenocarcinoma." (PMID 41000374, 2025).
lung carcinoma (5 papers, 2022 to 2025). "The aims of this study were to elucidate the function of TRIM46 in lung cancer and chemo-resistance of lung cancer cells, and to decipher what molecular pathways were necessary for such effects and the underlying mechanisms." (PMID 35354796, 2022). "Similarly, TRIM46 has been shown to promote chemoresistance in lung cancer and enhance osteosarcoma cell survival, supporting its role in cancer progression." (PMID 39937005, 2025). "The findings highlighted the importance of TRIM46/PHLPP2/AKT signaling which might be helpful in developing new drugs for lung cancer treatments." (PMID 35354796, 2022). "However, whether TRIM46 is amplified and the role of TRIM46 amplification in lung cancer are largely unknown." (PMID 35354796, 2022). "Nevertheless, the function of TRIM46 in lung cancer especially LUAD is largely unknown." (PMID 35354796, 2022). "However, the function of TRIM46 in lung cancer is largely unknown." (PMID 35354796, 2022). "In lung cancer, TRIM46 activates AKT/HK2 signaling by modifying PHLPP2 ubiquitination to promote glycolysis and chemoresistance, which reflects the importance of TRIM46/PHLPP2/AKT signaling in lung cancer and provides a new strategy for lung cancer treatment." (PMID 36249749, 2022). "In conclusion, our data highlight the importance of TRIM46/PHLPP2/AKT signaling in lung cancer and provide new insights into therapeutic strategies for lung cancer." (PMID 35354796, 2022). "Studies have found that Tripartite Motif-Containing 46 (TRIM46) mediates the ubiquitination of PH Domain and Leucine Rich Repeat Protein Phosphatase 2 (PHLPP2) via its PH domain, thereby activating the AKT/HK2 signaling pathway and ultimately promoting chemoresistance in lung cancer cells." (PMID 41463095, 2025).
osteosarcoma (4 papers, 2021 to 2025). A usually aggressive malignant bone-forming mesenchymal neoplasm, predominantly affecting adolescents and young adults. "In osteosarcoma, deletion of tripartite motif containing 46 (TRIM46) suppresses the activity of tumor cells, inhibits cellular cycle, and induces cellular apoptosis, whereas upregulation of TRIM46 displays the opposite effect." (PMID 34881275, 2021). "On the other hand, TRIM46 acts as an oncogene in osteosarcoma by interacting with and ubiquitinating peroxisome proliferator-activated receptor alpha (PPARα), resulting in the activation of the NF-κB signaling pathway." (PMID 33717417, 2021). "TRIM46 promoted cell growth and inhibited apoptosis of osteosarcoma cells by activating NF-κB signaling pathway through the ubiquitination of PPAR (Peroxisome proliferator-activated receptor)." (PMID 33717417, 2021). "In addition, TRIM46 can inducing the ubiquitination of PPAR to activate the NF-κB signaling pathway, increasing cell viability and inhibiting the apoptosis of osteosarcoma cells, so TRIM46 is considered a potential oncomarker of osteosarcoma." (PMID 36249749, 2022).
ovarian carcinoma (3 papers, 2015 to 2025). A malignant neoplasm originating from the surface ovarian epithelium. "GSEA revealed a significant enrichment of the Wnt/β-catenin pathway, which is closely associated with ovarian cancer cells with high TRIM46 expression." (PMID 39937005, 2025). "Furthermore, TRIM46 was highly expressed in late-stage ovarian cancer patients and was associated with poor prognosis." (PMID 39937005, 2025). "Furthermore, elevated TRIM46 expression in advanced ovarian cancer patients and its association with poor prognosis suggest that TRIM46 could serve as both a prognostic biomarker and a therapeutic target." (PMID 39937005, 2025). "Reparixin significantly reduced OC-MQ-induced TRIM46 expression and suppressed the invasion of ovarian cancer cells." (PMID 39937005, 2025). "Our results demonstrate for the first time that TAMs enhance TRIM46 expression in ovarian cancer cells." (PMID 39937005, 2025). "Knockdown of TRIM46 significantly decreased the nuclear translocation of β-catenin in ovarian cancer cells, suggesting that TRIM46 expression is positively associated with activation of the Wnt/β-catenin pathway." (PMID 39937005, 2025). "Treatment with CHIR99021, a Wnt/β-catenin activator, restored both invasion and mesenchymal marker expression in TRIM46-depleted ovarian cancer cells." (PMID 39937005, 2025). "Here, we identified that tripartite motif-containing 46 (TRIM46) is significantly upregulated in ovarian cancer cells treated with a conditioned medium derived from macrophages stimulated by ovarian cancer cells (OC-MQs)." (PMID 39937005, 2025). "In this study, we examined the gene expression patterns of ovarian cancer cells stimulated by macrophages and identified TRIM46 as a key player in TAM-facilitated invasion." (PMID 39937005, 2025). "To clarify the mechanism by which TRIM46 stimulates enhanced ovarian cancer cell invasion, we performed a gene set enrichment analysis (GSEA)." (PMID 39937005, 2025). "Survival analysis indicated that elevated TRIM46 expression correlated with reduced overall survival and progression-free survival in ovarian cancer patients." (PMID 39937005, 2025). "To explore the clinical significance of TRIM46, we analyzed publicly available datasets and found that TRIM46 expression was significantly higher in advanced-stage ovarian cancer tissues compared to early-stage disease." (PMID 39937005, 2025). "In conclusion, this study sheds light on the pro-metastatic role of TRIM46 in ovarian cancer and its regulation by TAMs via the CXCL8-CXCR1/2 axis." (PMID 39937005, 2025). "In this study, TRIM46 knockdown significantly reduced TAM-induced ovarian cancer invasion, underscoring its pro-metastatic function." (PMID 39937005, 2025). "In ovarian cancer cells, TRIM46 knockdown suppressed the OC-MQ-induced upregulation of mesenchymal marker mRNA." (PMID 39937005, 2025). "To evaluate whether CXCL8-mediated ovarian cancer cell invasion involves TRIM46 upregulation, we pre-treated ovarian cancer cells with reparixin, a CXCR1/2 inhibitor." (PMID 39937005, 2025). "TRIM46, a member of the TRIM protein family, has been implicated in various cancers, but its specific role in ovarian cancer was previously unknown." (PMID 39937005, 2025). "Importantly, the inhibition of TRIM46-mediated β-catenin nuclear translocation and ovarian cancer cell invasion was reversed by CHIR99021, a Wnt/β-catenin activator." (PMID 39937005, 2025). "Nevertheless, the function of TRIM46 in ovarian cancer remains largely uninvestigated." (PMID 39937005, 2025). "To determine whether the upregulation of TRIM46 in OC-MQ-facilitated ovarian cancer cells contributes to cell invasion, we performed an invasion assay following TRIM46 knockdown using siRNAs." (PMID 39937005, 2025). "Mechanistically, TRIM46 promotes Wnt/β-catenin signaling, enhancing EMT and invasion in ovarian cancer cells." (PMID 39937005, 2025).
ovarian carcinoma (continued). "In our study, pre-treatment with reparixin, a CXCR1/2 inhibitor, reduced CXCL8-induced TRIM46 expression and cancer cell invasion, further implicating the CXCL8-CXCR1/2 axis in ovarian cancer metastasis." (PMID 39937005, 2025). "Exploring how TRIM46 regulates other components of the TME, including stromal cells and immune components, could provide a more comprehensive understanding of its role in ovarian cancer progression." (PMID 39937005, 2025).
Clear Cell Renal Cell Carcinoma (2 papers, 2021 to 2024). "Lastly, auto-antibodies against TRIM46/TRIFIC have been proposed as a biomarker of paraneoplastic CNS disorders and clear-cell renal-cell carcinoma." (PMID 39205302, 2024). "However, the clinical value and potential functions of tripartite motif containing 46 (TRIM46) in clear cell renal cell carcinoma (ccRCC) remained largely unclear." (PMID 34881275, 2021).
Hyperglycemia (2 papers, 2022). An increased concentration of glucose in the blood. "Persistent hyperglycemia is closely related with DR, and thus it is worthwhile to explore the possible functions of TRIM46 during longer-term stimulation with HG." (PMID 36064447, 2022). "It has been reported by other studies that hyperglycemia could reduce GPX4 expression by inactivating the Nrf2/GPX4 pathway or facilitating GPX4 ubiquitination by TRIM46." (PMID 36290619, 2022).
serous ovarian carcinoma (2 papers, 2019 to 2021). "The chimeric RNAs generated from tripartite motif containing 46 (TRIM46) with MUC1 and KRTCAP2 have been clinically implicated in high-grade serous ovarian carcinoma." (PMID 34722520, 2021). "TRIM46 also contributed to a classifier that identified subtypes of high-grade serous ovarian carcinoma." (PMID 32117427, 2019).
triple-negative breast carcinoma (2 papers, 2021 to 2024). An invasive breast carcinoma which is negative for expression of estrogen receptor (ER), progesterone receptor (PR), and human epidermal growth factor receptor 2 (HER2). "In the CNA landscape of early triple-negative breast cancer (eTNBC) population, TRIM46 (10.8%) dominates as a focal amplification alteration, while PTEN (5.4%) dominates as a homozygous deletion." (PMID 39090361, 2024).
diabetes (1 paper, 2024). "Although the same lead SNP (rs11264341) in MUC1/TRIM46 did not provide evidence of a causal relationship between serum uric acid and incident diabetes, in people without a history of diabetes." (PMID 38279093, 2024).